GPX2 (glutathione peroxidase 2)
Diseases named in the same sentence as GPX2 in open-access papers (continued):
Sharing a sentence is not in itself a finding about the gene and the disease.
tumor (continued). "This was expected as oncogene-enriched subtype tumours exhibited more aggressive tumour growth and had an increased expression of gene mutations involved in cell proliferation (ERBB2, SLC44A4, EPCAM, CLDN3, and CLDN4), cell differentiation (ELF3 and GPX2), and mucin production (KRT20)." (PMID 36723696, 2023). "Additionally, GPX2 is highly expressed in many tumors and can promote tumor growth." (PMID 35721499, 2022). "When the Wnt pathway is dysregulated, GPX2 may promote tumor growth." (PMID 36324584, 2022). "Hence, GPx2 KD promotes a glycolytic switch that drives the bulk of the tumor." (PMID 35193955, 2022). "Interestingly, tumor cells positive for p-AMPK and GLUT1 were enriched at the interface of normoxic and hypoxic regions of the GPx2 KD tumor, where both metabolic modalities may be needed." (PMID 35193955, 2022). "Interestingly, tumor growth of BC31 cells subcutaneously transplanted in nude mice was significantly caused the induction of apoptosis, as well as inhibition of angiogenesis and SqD by GPX2 down-regulation." (PMID 29662611, 2018). "Hence the expression of GPX2 protein was significantly up-regulated within ESCC tumour tissues." (PMID 27388201, 2016). "Reducing GPX2 expression in rat HCC cells leads to decreased migration; tail vein injection of cells with knocked down GPX2 results in reduced tumor formation capability and fewer lung metastases." (PMID 40051627, 2025). "Single cell transcriptomics unravelled dramatic effects of GPx2 KD on EMT, resulting in tumour subpopulations drifting through an EMT continuum." (PMID 38238426, 2024). "By acting on GPX2 and scavenging excessive oxygen free radicals, NMRAL2P can also shield tumor cells from oxidative injury." (PMID 37810778, 2023). "CDK1, ECT2, EZH2, GJB2, GPR37, GPX2, and GPX8 mRNA expression was up-regulated in the tumor group (p < 0.001), whereas GPX3, HYAL1, and TLR4 mRNA expression was down-regulated in the tumor group (p < 0.001) compared with those in the normal group." (PMID 37689745, 2023). "The expression of CDK1, ECT2, GJB2, GPR37, GPX2, and GPX8 gene was up-regulated in the tumor group (p < 0.001), whereas the expression of TLR4 was down-regulated in the tumor group (p < 0.001) when compared with those in the normal group." (PMID 37689745, 2023). "Of note, by inputting the differentially expressed genes by GPx2 KD in cluster 5 into IPA, we identified overrepresented pathways in this cluster that were similar to those in the bulk of the tumor, including OXPHOS and glycolysis." (PMID 35193955, 2022). "To identify the overrepresented upstream regulators that may explain the GPx2 KD-stimulated changes in gene expression, we analyzed the top 583 genes that were significantly differentially expressed in the GPx2 KD relative to the control tumor, using Ingenuity Pathway Analysis (IPA)." (PMID 35193955, 2022). "Importantly, to determine whether the biological effects caused by GPx2 loss were not simply due to tumor cell hyperproliferation causing crowding and hypoxia, we analyzed these effects in similarly-sized GPx2 KD and control tumors." (PMID 35193955, 2022). "This revealed that GPx2 KD further enriched cluster 5 in basal/mesenchymal-like genes (KRT14, ITGA6, FGFR1, COLA9A3, S100s) relative to cluster 5 in control tumor." (PMID 35193955, 2022). "KD of GPx2 in MDA-MB-361 cells by two independent shRNAs stimulated increases in ROS levels and Matrigel invasion, as well as in tumor growth in vivo." (PMID 35193955, 2022). "We also detected two WNT mediators of GPX2 and OLFM4, which can be activated by Lgr5 to drive tumor progression." (PMID 34764257, 2021). "The expression levels of ALOX12B, GPX2, DDIT4, GDF15, and RRM2 in tumor tissues were significantly higher than those in the normal lung tissues." (PMID 34307361, 2021).
tumor (continued). "This is in line with the observation that GPx2 is not only expressed in the GIT, but also in various tumor cells of epithelial origin, in the premalignant Barrett ́s esophagus leading to esophageal adenomas, in colorectal adenomas and CRCs." (PMID 29416634, 2018). "On one hand, GPX2 suppresses the activity of cyclooxygenase 2 (COX-2), an inducible enzyme responsible for converting arachidonic acid to prostaglandins, thereby silencing inflammation and inhibiting tumor cell migration and invasion." (PMID 41300456, 2025). "Furthermore, heatmap analysis revealed that TREX1 and RRM2 expression levels were significantly higher in tumor tissues compared to normal tissues, whereas GPX2, DUOX1, and DUOX2 were expressed at lower levels in tumor tissues." (PMID 41346575, 2025). "Consistent with the A549-derived results, tumor growth measurement revealed that GPX2 silencing potentiated gefitinib-induced tumor growth inhibition in HCC827-GR-derived nude mice, with tumor sizes and endpoint weights demonstrating a synergistic effect of GPX2 knockdown plus gefitinib." (PMID 40533443, 2025). "Similarly, GPx2 OE tumours, showed high E-CAD and low N-CAD/KRT14/VIM expression relative to control PyMT2 tumours." (PMID 38238426, 2024). "Indeed, echinomycin-treated GPx2 KD tumours showed dramatic reductions in p63 and KRT14 levels, resulting in KRT8-enriched tumours, indicative of luminal differentiation." (PMID 38238426, 2024). "Remarkably, cells lacking Gpx-2 exhibited a lack of differentiation capacity and developed slow-growing, undifferentiated tumours." (PMID 37834097, 2023). "Our scRNA-seq data confirmed a fivefold reduction in GPx2 mRNA in the GPx2 KD tumor and violin plots confirmed a dramatic increase in HIF1α and VEGFA mRNAs in most of the clusters that make up the GPx2 KD tumor." (PMID 35193955, 2022). "Interestingly, compared to the regularly shaped PyMT tumor vessels, which displayed colocalized lectin-TRITC with endomucin-FITC in most vessels (SIAppendix), GPx2 KD tumor vessels were devoid of lectin-TRITC at the endothelial cell membrane." (PMID 35193955, 2022). "Overall, GPx2 KD tumors contained a significantly higher percentage of cells expressing GLUT1, and a lower percentage of cells expressing p-AMPK relative to control tumors, consistent with the Warburg effect in the bulk of the tumor." (PMID 35193955, 2022). "In contrast to the association of plasma GPx with clinical outcomes, high GPx2 expression in patients’ HCC tissue was positively rather than negatively correlated with α-fetoprotein level, tumor size, and HCC recurrence." (PMID 34836325, 2021). "Genes related to lipid metabolism and immune response that are associated with poor prognosis were discovered including HMGCS2, GPX2 and CD36, which may provide clues for tumor biomarkers or therapeutic targets." (PMID 31074374, 2019). "In this study, we found that the expression of GPX2 protein was significantly up-regulated within ESCC tumour tissues compared with non-tumour tissues." (PMID 27388201, 2016). "Convincingly, GPX2 protein was significantly overexpressed within ESCC tumour tissues compared with non-tumour tissues in this study." (PMID 27388201, 2016). "Under equal-weight protein samples, western blotting results showed that GPX2 was obviously overexpressed within ESCC tumour tissues compared with non-tumour including PN and DN." (PMID 27388201, 2016). "A significant higher expression level of GPX2 was detected in tumour tissues compared to that in non-tumour tissues (P < 0.001)." (PMID 27388201, 2016). "While tumor numbers were similarly low in GPx2-KO mice irrespective of the selenium status (−Se: 5, +Se: 5, ++Se: 3), tumor numbers in WT mice were higher in the −Se and ++Se groups than in the +Se group (−Se: 14 and ++Se: 13 vs. +Se: 7)." (PMID 23977205, 2013).
tumor (continued). "Although tumor incidence was not significantly different between the experimental groups, −Se and ++Se GPx2-KO mice had significantly lower tumor numbers than WT mice on the same diets." (PMID 23977205, 2013). "Moreover, immunohistochemistry results of human HCC samples indicate that GPX2 is more highly expressed in tumor sites than in adjacent non-tumor tissues." (PMID 40051627, 2025). "Indeed, echinomycin-treated GPx2 KD tumours were negative for GLUT1, pAMPK and KRT14 but retained KRT8 expression relative to vehicle-treated GPx2 KD tumours which were positive for all four markers." (PMID 38238426, 2024). "Indeed, the GPx2 KD tumor expressed notably higher levels of glucose transporter GLUT1 (SLC2A1), aldolase-A (ALDOA), phosphoglycerate kinase (PGK1), and lactate dehydrogenase A (LDHA) than in the control tumor." (PMID 35193955, 2022). "Additionally, it would be interesting to determine the levels of Gpx-2 protein using the Western blot method in a larger group of patients, as well as to examine the mRNA content in tissue samples from both the tumour and the surrounding area without neoplastic lesions." (PMID 37834097, 2023). "While tumor cells do not have high expression of NFE2L2 relative to myeloid cells, elevated expression occurs downstream of the Nrf2 pathway (NQO1, GPX2), which regulates oxidative damage repair." (PMID 35995947, 2022). "According to the IHC results of GPX2 protein expression within ESCC tumour tissues, we divided ESCC patients into two groups, namely GPX2-positive expression (GPX2+) group and GPX2-negative expression (GPX2-) group." (PMID 27388201, 2016).
infection (12 papers, 2007 to 2024). The state of being infected such as from the introduction of a foreign agent such as serum, vaccine, antigenic substance or organism. "For functional annotation of KEGG pathway enrichment, in the acute infection stage, we observed significant enrichment of upregulated mRNAs (Gpx2 and Gpx3) in the glutathione metabolism pathway." (PMID 38229193, 2024). "GPX2 is up-regulated both at 3 and 4.5 h post trophozoite infection (3.1 and 4.4-fold change, respectively)." (PMID 35573800, 2022). "Following infection glutathione peroxidase 2 was increased in both ASL and AFL groups which would indicate a requirement to remove reactive products of increased protein turnover and oxidation." (PMID 20602791, 2010). "Interestingly, the expression of GPx-1 increased during the first 3 days of infection, but GPx-2 was downregulated during invasion." (PMID 37210527, 2023). "Similarly, infection-induced expression of Duox2 and Gpx2 was also attenuated by dietary chicory, albeit not significant." (PMID 37316905, 2023).
CNS tumors (1 paper, 2021). "Our model suggested that GPX2 was positively related to the patient OS, indicating that protection against oxidative damage might exist in CNS tumors." (PMID 34093788, 2021).
head and neck tumor (1 paper, 2023). "The results showed that the decrease in the migration, invasion, and proliferation of head and neck tumor cells caused by GPX2 knockdown was reversed by Tempol (1 mM)." (PMID 37810778, 2023).
infectious disease (1 paper, 2022). A disorder directly resulting from the presence and activity of a microbial, viral, or parasitic agent in humans. "The GSEA analysis showed that GPX2 expression was mainly related to EMT and infectious disease biology, including the EMT and Wnt signaling pathways." (PMID 36312753, 2022).
GPX2 also shares sentences with these, for which no sentence is quoted: head and neck cancer (3 papers); adenocarcinoma (2); diabetes (2); Barrett esophagus (1); benign tumours (1); brain cancer (1); cervical cancer (1); cholangiocarcinoma (1); Cognitive impairment (1); colorectal tumor (1); dysplasia (1); hippocampal atrophy (1); hyperplasia (1); injury (1); leukemia (1); liver cancer (1); liver fibrosis (1); lymphoma (1); mesothelioma (1); neuroblastoma (1); ovarian carcinoma (1); prostatic adenocarcinomas (1); renal cell carcinoma (1); sarcoma (1); seminoma (1); Sepsis (1); serous ovarian carcinomas (1); squamous cell carcinoma (1); type 2 diabetic (1); uveal melanoma (1).